RELA (RELA proto-oncogene, NF-kB subunit)
Diseases named in the same sentence as RELA in open-access papers (continued):
Sharing a sentence is not in itself a finding about the gene and the disease.
breast cancer (72 papers, 2007 to 2026). A primary or metastatic malignant neoplasm involving the breast. "In research, the lncRNA TROJAN led to CDK2 upregulation by linking to NKRF and blocking its inhibition on RELA/p65, so contributing to the decreased response of ER+ breast cancer cells to CDK4/6is." (PMID 40244377, 2025). "We determined the effect of NF-κB activation in DAB2IP-low Luminal A breast cancer by profiling RELA, RELB, and NFKB2 genomic binding and gene expression using ChIP-Seq in stable DAB2IP knockdown and control T47D cells." (PMID 39418101, 2024). "In conclusion, our immunoprecipitation experiment captured interactions of RELA with other NF-κB factors and regulators of NF-κB pathway and extended the known interactome of RELA in breast cancer cells." (PMID 38417630, 2024). "Previously, we showed that cell shape is a regulator of RELA dynamics in breast cancer cell lines and that breast cancer cells with mesenchymal cell shape (protrusive with low cell–cell contacts) have higher RELA nuclear translocation." (PMID 39110005, 2024). "Our study confirms at several levels that SHTN1 and KIF5B interact with both PRMT5 and RELA in luminal A breast cancer cells." (PMID 38417630, 2024). "We also identified that RELA activity, coupled to cell shape, is predictive of breast cancer progression." (PMID 39110005, 2024). "The immunoprecipitation experiment performed with anti-RELA antibody further expanded the known protein interactome of RELA in MCF-7 breast cancer cell line." (PMID 38417630, 2024). "Recently, CECR2 was identified as a critical epigenetic regulator that interacts with acetylated RelA, increasing the expression of NF-κB target pro-inflammatory genes and driving breast cancer metastasis." (PMID 39713312, 2024). "To further validate that the transcriptional activity of RelA in ER+ breast cancer cells is nearly restricted to HD conditions, we silenced RelA with CRISPR-Cas9 using two different single guide RNAs (gRNA)." (PMID 37450351, 2023). "Overall, the mechanism by which ER facilitates RelA phosphorylation and how RelA phosphorylation affects RelA chromatin binding in ER+ breast cancer cells warrant additional investigation." (PMID 37450351, 2023). "Silencing of RelA and RelB decreases the organotropic ability of exosomes in vivo and significantly reduces their ability to promote breast cancer migration and invasion." (PMID 35765040, 2022). "The expression of RELA is higher in patients with TNBC than in patients with other breast cancer subtypes (luminal A, luminal B, and HER2-positive) and in normal breast tissue." (PMID 35955813, 2022). "RELA has shown an increased methylation level that is significant in the progression of breast cancer, HMOX2 has shown an increased hypomethylation in endometriosis, while EZH2 mediates histone modification H3K27m3 and causes several cancers." (PMID 34788504, 2021). "c-Jun and p65/RelA transcription factors targeting BEX2 are being phosphorylated in breast cancer cells." (PMID 34803456, 2021). "RelA had been used as an evaluator to evaluate the role of NF-κB activation in various tumors, including lung adenocarcinoma, breast cancer, liver cancer, CRC, and so on." (PMID 34867383, 2021). "We found a dose-dependent inhibition of RPM-based spheroid formation by DEX, that was independent from RelA nuclear translocation which was described for DEX-treated breast cancer cells." (PMID 32033410, 2020). "We analyze the DNA methylation status of the NFKB1 gene and the RELA gene in breast cancer using pyrosequencing." (PMID 31382678, 2019). "Our results suggest that methylation of the RELA gene contributes to expression of NF-κB1 in response to TNF-α in breast cancer." (PMID 31382678, 2019). "In conclusion, we found that the level of the RELA gene methylation was significantly related to the levels of NF-κB1 transcripts in breast cancer with positive expression of TNF-α." (PMID 31382678, 2019).
breast cancer (continued). "In this study, we analyzed the methylation status of the NFKB1 and the RELA gene in breast cancer, and found that the methylation level of the RELA gene was significantly correlated with the level of NF-κB1 transcripts under the influence of TNF-α." (PMID 31382678, 2019). "The miR-520/373 family has also been shown to act as tumor suppressors in breast cancer, by targeting the RELA/p65 NF-κB subunit." (PMID 29601548, 2018). "We demonstrated that HOXA-AS2 controls the expression of miR-520c-3p target genes, TGFBR2 and RELA, in breast cancer cells." (PMID 28545023, 2017). "In conclusion, we found that highly expressed HOXA-AS2 down-regulates miR-520c-3p, then release its targets, TGFBR2 and RELA, and promotes proliferation, migration and invasion of breast cancer cells." (PMID 28545023, 2017). "Gene expression analysis in both normal mammary epithelial and breast cancer cells revealed that PR inhibited NFκB target genes through interacting with DNA-bound RelA/p65, resulting in transcription inhibition of NFκB target genes." (PMID 25866757, 2015). "Studies have demonstrated that ER interacts with RelA/p65, a member of the NFκB family, and synergistically regulates expression of a group of genes that are important in regulating breast cancer cell survival and chemoresistance." (PMID 25866757, 2015). "In breast cancer, NF-kB activation has been measured by nuclear accumulation of RelA in tumor cells." (PMID 26460486, 2015). "We examined RelA expression in sections of breast cancer tissue from a cohort of tumors that contained examples of each major subtype of disease." (PMID 26460486, 2015). "Overexpression of RelA in a breast cancer cell line or pro-B cells, and expressing cRel in HELA cells and RelB in murine fibroblasts retards proliferation." (PMID 26460486, 2015). "NF-kB Rel proteins with a trans-activating domain negatively regulate proliferation, albeit in specific cell types: RelA in murine fibroblasts, pro-B cells and breast cancer cells, RelB in murine fibroblasts and cRel in HELA cells." (PMID 26460486, 2015). "This evidenced that PAR1 activity contributed to LEC migration and CCID formation, which was stimulated by RELA/NFKB1 - MMP1 signals generated in MDA-MB231 breast cancer spheroids." (PMID 26513020, 2015). "The elevation of NF-κB activity was found in lapatinib-treated HER2-positive breast cancer cells, and targeting RelA (p65) protein expression enhanced the lapatinib-induced apoptosis." (PMID 24216290, 2013). "We further examined the protein expression of RelA/p65 by IHC in human breast cancer specimens and showed a consistent pattern of over-expression in more aggressive, poorly differentiated tumors." (PMID 22952718, 2012). "We examined the protein expression of RelA/p65 by immunohistochemical analysis in 89 cases of human breast cancer, as well as 5 normal breast tissues." (PMID 22952718, 2012). "In summary, this study shows that BEX2 has a functional interplay with c-Jun and p65/RelA in breast cancer." (PMID 20482821, 2010). "Early-stage primary breast cancer selected for lower ER content showed two- to fourfold increased NFkB1 and RelA DNA binding over a second set of primary breast cancer with higher ER content." (PMID 17700572, 2007). "miR-138 and members of the miR-520/373 family were shown to target RELA in breast cancer." (PMID 38539461, 2024). "For instance, RELA-bound genes such as NOP10, a member of the H/ACA small nucleolar RNP (snoRNP) gene family, and TPI1, an important glycolytic enzyme are associated with poor prognosis in breast cancer." (PMID 39418101, 2024). "The decreased abundance of ANXA4 in RELA immunoprecipitate after NF-κB inhibition in our study suggests that ANXA4 interplays with NF-κB also in the breast cancer and could promote metastatic behavior of breast tumors via NF-κB pathway." (PMID 38417630, 2024).
breast cancer (continued). "The RelA subunit of NF-κB is reported to be activated in breast cancer cell lines, whereas breast tumours are shown to exhibit an absence or low level of nuclear RelA, in contrast to activated c-Rel, NF-κB1 and NF-κB2 along with bcl2 expression, as compared to nontumorigenic adjacent tissue." (PMID 36899924, 2023). "To test the direct transcriptional effects of RelA/NF-κB signaling in ER+ breast cancer in HD conditions, we integrated the RelA ChIP-seq (binding sites in HD conditions) and RNA-seq (differential expression between HD and E2 conditions), using the BETA algorithm." (PMID 37450351, 2023). "However, other studies reported that overexpression of RELA was associated with a reduction in tumorigenicity and activation of apoptosis in the MCF7 ADR human breast cancer cell line." (PMID 37624039, 2023). "Additionally, it has been reported that the overexpression of the RelA/p65 gene in human colon cell lines and in human breast cancer, M14 melanoma, and lung adenocarcinoma cell lines is associated with the promotion of apoptosis." (PMID 36012158, 2022). "In breast cancer cells, transfection of RelA shRNA reduced proliferation." (PMID 30061500, 2018). "We identified TGFBR2 and RELA as direct targets of miR-520c-3p in breast cancer." (PMID 28545023, 2017). "NFκB exists as a heterodimer composed of RelA (p65) and NFκB1 (p50) subunits in most cells, where it regulates the expression of multiple genes and contributes to the pathogenesis of various diseases, including breast cancer." (PMID 26696754, 2015). "Of note, in radioresistant MCF-7 breast cancer cells, RelA is able to inhibit the MAPK pathway." (PMID 25893721, 2015). "We tested whether ING4 protein expression levels affected phosphorylation of p65/RelA in breast cancer cell lines in vitro." (PMID 23056468, 2012). "Specifically, our discovery of suspension-induced up-regulation of TrkB and NTF3 in breast cancer cells via NF-κB supports earlier work showing that polo-like kinase 1 (PLK1) is transcriptionally activated by RelA in suspended esophageal squamous cell carcinomas, leading to anoikis resistance." (PMID 23185507, 2012). "hTREX84 and the RelA/p65 subunit of NF-κB could also be mutually activated in aggressive breast cancer." (PMID 22952718, 2012). "Since our previous studies found that hTREX84 was highly expressed in the cell nucleus especially in poorly differentiated and more aggressive human breast cancers, we asked whether RelA/p65 may also be expressed in a similar manner." (PMID 22952718, 2012). "Moreover, NFKB1/RELA induces breast cancer progression by upregulating ETS1." (PMID 34335799, 2021). "Moreover, miR-7 suppressed CD44 and ESA by directly inhibiting the NF-κB subunit RELA and slug in breast cancer cell lines and in BCSC-driven xenografts, which confirmed the antitumor activity in mice injected with miR-7 agomir or stably infected with lenti-miR-7." (PMID 32143670, 2020). "Consequently, it has been shown that suppression of AKR1B1 inhibits the expression of RelA and Twist2 while its overexpression could induce RelA and Twist2 in various cell lines of breast cancer." (PMID 32633024, 2020). "However, lipopolysaccharide (LPS) is known to induce NF-κB activation in breast cancer cells, so we treated 182R-6 cells with LPS, alone or in combination with the NF-κB inhibitor sc-514, and examined the expression of miR-22 and nuclear RelA/p65." (PMID 30057418, 2018). "Also in MCF-7 breast cancer cells RELA and NFKB1 triggered CCID formation." (PMID 26513020, 2015). "Nonetheless, other studies that have tagged RELA endogenously did detect oscillations, including MEFs and MCF7 breast cancer cells." (PMID 39110005, 2024).
breast cancer (continued). "The ubiquitination of p65 (RELA) and its degradation by E3 ligase, FBXW2, leads to suppressed breast cancer stemness and tumorigenesis." (PMID 38201482, 2023). "A large-scale analysis of human breast cancer using the TIMER and GEPIA2 databases showed a positive correlation among TNF-α, RELA, or v-rel avian reticuloendotheliosis viral oncogene homolog A and ATX in breast cancer patients." (PMID 38201482, 2023). "The XBP1s contributes to the development of endocrine-resistant breast cancer by upregulating the expression of BCL2, p65/RelA, NCOA3, RRM2, CDC6, and TOP2A." (PMID 38203358, 2023). "RelA and RelB are able to decrease the levels of MCAM and CD146 adhesion molecules in the release of EVs, leading to breast cancer metastasis." (PMID 35765040, 2022). "The application of PDTC to the Her2-amplified breast cancer cell line SKBR3 induces inhibition of the IκB ubiquitin ligase resulting in an enhanced interaction of PTPIP51 and RelA." (PMID 32518680, 2020). "All applied concentrations of IKK-16 significantly reduced the RelA/PTPIP51 interaction (0.5 μM p < 0.01; 5 μM p < 0.05) in the breast cancer cell line SKBR3." (PMID 32518680, 2020). "The findings from this study uncover the molecular mechanisms by which miR-7 inhibits XIST, modulates the miR-92b/Slug/ESA axis, and decreases the RELA and CD44 expression, resulting in a reduced BCSC subset and breast cancer growth inhibition." (PMID 32143670, 2020). "In primary breast cancer tissues, the mean methylation level was 1.40 ± 0.90% for the NFKB1 gene and 1.49 ± 0.50% for the RELA gene, while that of two genes in normal mammary tissues was 1.51 ± 0.66% and 1.60 ± 0.19%, respectively." (PMID 31382678, 2019). "We recently reported that in aggressive ER- breast cancer, EZH2 complexes with RelA/RelB and binds to the Notch1 promoter to activate transcription independent of its methyltransferase activity." (PMID 30022044, 2018). "In summary, our study suggests that the crosstalk between NFATc2, NFKB1/RELA, and CRE region regulates Ets1 gene transcription in metastatic breast cancer cells." (PMID 30467308, 2018). "Our results demonstrated that the HOXA-AS2/miR-520c-3p axis controls the expression of RELA, suggesting a role for the HOXA-AS2/miR-520c-3p in breast cancer through the NF-κB signaling pathway." (PMID 28545023, 2017). "In the present study, we also explored the mechanism of the HOXA-AS2/miR-520c-3p axis in breast cancer and detected the influences of HOXA-AS2 on the targets (TGFBR2 and RELA) of miR-520c-3p." (PMID 28545023, 2017). "Another member of the NF- κB related factors family is RelA which is found to collaborate with SMAD3, AHR and c-Myc each of which is known to be involved in breast cancer." (PMID 26627005, 2015). "The physical interaction of RelA and AHR is important for the activation of the c-Myc oncogene in breast cancer cells." (PMID 26627005, 2015). "RELA, RELB, CREL, NFKB1 and NFKB2, and the upstream regulators NEMO and NIK were knocked-down in lymph endothelial cells (LECs) and in MDA-MB231 breast cancer spheroids to study the contribution of NF-κB in vascular barrier breaching." (PMID 26513020, 2015). "Consistent with the inverse relationship between ING4 and p-p65/RelA levels in breast tumors, over-expression of ING4 resulted in the inhibition of p65/RelA phosphorylation in the T47D and MCF7 breast cancer cell lines." (PMID 23056468, 2012). "Conversely, ectopic expression of ING4 inhibited p65/RelA phosphorylation in T47D and MCF7 breast cancer cells." (PMID 23056468, 2012). "Breast cancer tissue sections were co-stained with murine mAb (Kao2) to PL2L proteins and rabbit mAb to RelA/p65, a subunit of NF-κB." (PMID 20975993, 2010).
breast cancer (continued). "Furthermore, RELA, a subunit of the NFKB1, has also been identified as a target for preventing NFKB1-driven tumors, as this subunit is more highly expressed in breast cancer compared to adjacent tissues." (PMID 37686072, 2023). "Thus, there were positive correlations among TNF-α, RELA and ATX, but these relationships need to be investigated further to understand their roles in the progression of breast cancer metastasis and patient survival." (PMID 38201482, 2023). "Recently, NF-κB p65 (RELA) gene expression was reported to be increased in TNBC compared to that in other subtypes, deeply involved in TNBC stem cell survival, and activated during the recurrence of breast cancers, including TNBC." (PMID 35955813, 2022). "Further analysis of mutual exclusivity showed that only one gene pair (NOTCH1-RELA) exhibited significant co-occurrence (p < 0.05) in the breast cancer study by the INSERM 2016 project, which indicated the pivotal role of NOTCH1 and RELA under tangeretin treatment." (PMID 34335799, 2021). "Based on the knowledge that NF-κB seems to play a crucial role in spheroid formation of MCF-7 breast cancer cells and that NF-κB subunit p65 (RelA) accumulates in thyroid cancer cells on the RPM, we decided to target RelA in μg-grown thyroid cancer cells using DEX." (PMID 32033410, 2020). "LDC3/Dynarrestin altered the regulation of the Tyr176 residue phosphorylation, the interaction with MAPK signaling and the link to NFκB signaling via RelA in breast cancer cells and in non-tumor HaCat cells all analogously." (PMID 31075141, 2019). "Compared with less metastatic cells (MCF-7), metastatic breast cancer cells (MDA-MB-231) have relatively open chromatin structure on the CRE, which facilitates direct binding of NFATc2 and NFKB1/RELA to enhance Ets1 expression and invasiveness of metastatic breast cancers, accordingly." (PMID 30467308, 2018). "Compared with the less metastatic breast cancer cells, metastatic breast cancer cells (MDA-MB-231) show open chromatin configurations in the CRE, which facilitates direct binding of NFATc2 and/or NFKB1/RELA complex to trans-activate Ets1 transcription." (PMID 30467308, 2018). "This was the likely reason why the activities of both pathways did not stimulate CCID formation beyond the activity of just RELA/NFKB1 in MDA-MB231 breast cancer cells and also in LECs." (PMID 26513020, 2015). "Interestingly, in ER- breast cancer, ESR1 (ERα), RELA, SP1, and AR exhibit the highest degree in the network." (PMID 25996148, 2015). "It is widely believed that NF-kB activation, and nuclear localization of RelA, is common in estrogen receptor-negative (ER-) breast cancers." (PMID 26460486, 2015). "In breast cancer cells, plitidepsin induces several early response genes such as c-JUN, JUNB, JUND, c-FOS, FOSB and FRA1, as well as RELA/p65, the major component of the nuclear transcription factor kappa B (NFkB), while also decreasing the cellular content of the c-MYC protein." (PMID 23697951, 2013). "The impact of RelA silencing on B2M was statistically significant, but the absolute difference was limited, which is consistent with the notion that other transcription factors, such as IRF1, facilitate the upregulation of B2M in ER+ breast cancer cells as in other cell types." (PMID 37450351, 2023).